RN7SL586P (RNA, 7SL, cytoplasmic 586, pseudogene)
Gene: Miscellaneous RNA gene on chromosome 14 (73,040,619 to 73,040,914, reverse strand). Ensembl gene ENSG00000241487.
Homologues: Orthologues: chimpanzee Metazoa_SRP (99% identical), macaque Metazoa_SRP (92% identical). Paralogues in human: RN7SL1 (85% identical), RN7SL2 (85% identical), RN7SL3 (84% identical), RN7SL45P (83% identical), RN7SL665P (82% identical), RN7SL709P (82% identical), RN7SL126P (81% identical), RN7SL448P (81% identical), RN7SL769P (81% identical), RN7SL191P (81% identical), RN7SL597P (81% identical), RN7SL444P (80% identical), and 707 more.